REELD1 (reeler domain containing 1)
Gene: Protein-coding gene on chromosome 4 (146,214,515 to 146,232,267, forward strand). Ensembl gene ENSG00000250673.
Subcellular location: Membrane
Gene Ontology:
Molecular function: protein binding
Cellular component: membrane
Homologues: Orthologues: chimpanzee REELD1 (98% identical), macaque REELD1 (91% identical), rabbit REELD1 (67% identical), pig REELD1 (63% identical), tropical clawed frog reeld1 (36% identical), Drosophila melanogaster CG8399 (15% identical), Caenorhabditis elegans C05D12.1 (10% identical), Drosophila melanogaster CG14515 (9% identical), Drosophila melanogaster l(2)34Fc (9% identical), Caenorhabditis elegans Y57G11A.4 (8% identical), Caenorhabditis elegans M03A1.8 (6% identical), Caenorhabditis elegans M03A1.3 (4% identical). Paralogues in human: FRRS1 (20% identical), FRRS1L (6% identical).